FOXP3 (forkhead box P3)
Diseases named in the same sentence as FOXP3 in open-access papers (continued):
Sharing a sentence is not in itself a finding about the gene and the disease.
breast carcinoma (continued). "This context encouraged us to investigate if Runx1 is able to modulate gene expression in mammary tumor cells, and whether this activity could be modulated by Foxp3 in normal epithelial cells." (PMID 26735887, 2016). "The main explanation may be that the favorable prognostic effect of FOXP3+ TILs in TNBC breast cancer may be primarily due to CD8+ T-cell infiltration." (PMID 26475790, 2015). "In addition, we also confirmed that numbers of tumor-infiltrating FoxP3+ cells in breast cancer were also positively correlated with tumor stages and lymph nodal status, but negatively correlated with RFS and OS." (PMID 25968569, 2015). "Therefore, the aim of this meta-analysis was to clarify the prognostic role of FOXP3 expression in operable breast cancer cases." (PMID 26305693, 2015). "However, other studies reported that Foxp3 acts as a tumor suppressor in breast cancer and prostate cancer." (PMID 25779374, 2015). "Furthermore, tumor draining lymph nodes of the both breast cancer models harbored high levels of FoxP3+Treg subset, which reached the maximal levels at the late cancer stage." (PMID 25968569, 2015). "However, the clinicopathological and prognostic significance of FOXP3+ TILs detection in patients with breast cancer remains controversial." (PMID 26475790, 2015). "The prognostic value of FoxP3+ Tregs in breast cancer is most frequently studied." (PMID 26462617, 2015). "One possible explanation may be that FOXP3+ TILs reflect tumor-induced immune evasion in breast cancers." (PMID 26475790, 2015). "To date, the prognostic significance of FOXP3+ TILs in breast cancer remains controversial." (PMID 26475790, 2015). "In addition, a direct interaction of FOXP3 with NF-κB p65 was identified to regulate a miR-146a-NF-κB negative feedback regulation loop in normal breast epithelial cells as well as in breast cancer cells." (PMID 26682271, 2015). "On multivariate survival analysis, a high level of FOXP3+ TILs was significantly associated with poor survival in ER+ breast cancers that lacked CD8+ T-cell infiltrates (hazard ratio (HR) = 1.30, 95% confidence interval (CI) = 1.02 to 1.66)." (PMID 25193543, 2014). "The prognostic importance of Foxp3 expression in patients with breast cancer has been investigated." (PMID 24562936, 2014). "We implemented this study to evaluate the prognostic significance of FOXP3+ TILs, in a population-based breast cancer cohort with long-term follow-up and detailed biomarker data defining the main intrinsic molecular subtypes and cytotoxic T-cell infiltrates in breast tumor tissues." (PMID 25193543, 2014). "However, in human breast cancer, nuclear expression levels of FOXP3 were found to be negligible in comparison to FOXP3-positive T-cells." (PMID 24725474, 2014). "Even within breast cancer, the prognostic significance of FOXP3+ TILs has been widely debated." (PMID 25193543, 2014). "FOXP3+ TILs are significantly associated with poor survival in ER + breast cancers lacking cytotoxic T-cell infiltrates." (PMID 25193543, 2014). "B7-H3 and Foxp3 can be regarded as markers of poor prognosis in breast cancer." (PMID 24562936, 2014). "Since it has been previously shown that FOXP3 is involved in breast cancer development, several studies have been conducted to investigate a SNP (rs3761548, C/A) in the promoter region of FOXP3 in patients with this neoplasia, but its exact role is not yet well understood." (PMID 24877082, 2014). "Our multivariate analyses stratified for presence or absence of CD8+ T-cell infiltration demonstrated that the favorable prognostic effect of FOXP3+ TILs in ER– breast cancer was only significant and independent in those having HER2+/ER– tumors with concurrent CD8+ T-cell infiltrates." (PMID 25193543, 2014). "Our findings may facilitate the selection of appropriate patient treatments and assist in the designing of FOXP3-targeted therapeutic strategies for breast cancer." (PMID 24649219, 2013).
breast carcinoma (continued). "Although FOXP3 expression was thought to be restricted to Treg, recently it has been elucidated that this transcription factor is also present in various types of tumor cells, including breast cancer." (PMID 23861693, 2013). "FOXP3 acts as a transcriptional repressor of oncogenes, HER-2/ErbB2 and S-phase kinase-associated protein 2 (SKP2), and FOXP3-regulated microRNAs suppress special AT-rich sequence-binding protein 1, whereas deletions of FOXP3 exons extinguish those suppressive function in a breast cancer cell line." (PMID 24155921, 2013). "Further, immunoblot analysis was carried out to evaluate the expression of p27, a pro-apoptotic cyclin D kinase inhibitor, which positively correlates with FOXP3 activity, and SKP2, a breast cancer oncogene known to be suppressed by FOXP3 transcriptional activity." (PMID 23341929, 2013). "Since these cytokines are known to influence the progression of breast cancer, the regulation of cytokine synthesis by nuclear FOXP3 may affect the interaction between tumor cells and their microenvironment and, subsequently, clinical prognosis." (PMID 24649219, 2013). "The expression pattern and role of FOXP3 in breast cancer has been more difficult to elucidate." (PMID 23341929, 2013). "Our data suggested that FOXP3 expression in tumor cells and TILs may be an effective prognostic marker in breast cancer patients and that FOXP3 localization in tumor cells is an important determinant of prognosis." (PMID 24649219, 2013). "On the otherhand, one TReQTL tag SNP (rs3790904) in the CEU population is associated (p-value = 8.1×10−7) with the DSTs of the X-linked breast cancer suppressor gene Foxp3 but is not significant in YRI (p-value = 0.89)." (PMID 22479588, 2012). "Furthermore, a predictive effect of breast cancer infiltration by FOXP3+ cells has also been reported." (PMID 22471961, 2012). "Increased FoxP3 expression and Treg cell elevation are generally considered to be poor outcome markers in various cancers, including Hodgkin’s lymphoma, follicular lymphoma, breast cancer, gastric malignancies, and ovarian cancers." (PMID 23071717, 2012). "Notably, infiltration by FOXP3+ lymphocytes in breast cancer has been proposed to represent an independent unfavorable prognostic factor, especially in the nodal positive subgroup and to correlate with tumor invasiveness." (PMID 22471961, 2012). "FOXP3 expression has also been reported in human breast cancer cells." (PMID 22471961, 2012). "In CEU, a TReQTL SNP was found to be associated with the DSTs of the X-linked breast cancer suppressor Foxp3 but is not significant in the YRI dataset." (PMID 22479588, 2012). "Intriguingly however, they also suggest that breast cancer infiltration by CD4-/FOXP3+ lymphocytes might represent an independent favorable prognostic factor." (PMID 22471961, 2012). "Our results implied that up-regulation of IDO in primary breast cancer may inhibit local immune surveillance and promote metastasis by favoring development and infiltration of Foxp3+ Tregs in the tumor microenvironment." (PMID 22110525, 2011). "Moreover, the same group observed a immune phenotype of basal-like breast cancer portraying a higher frequency of FoxP3-expressing T regulatory cells and characterized by poorer prognosis." (PMID 21875439, 2011). "Previous studies have pointed out that tumor infiltrating Foxp3+ Tregs may influence the clinical course of breast cancer." (PMID 19604349, 2009). "Our aim was to assess whether expression of Foxp3, a marker of Tregs, and IDO were linked with nodal metastasis in breast cancer patients." (PMID 19604349, 2009). "However, the prognostic significance of FOXP3+ TILs in breast cancer remains controversial." (PMID 40883317, 2025). "In addition, a high FoxP3 + TIL count was associated with an inferior outcome in patients with HER2 + Luminal B breast cancer, but not in the HER2 + /HR-negative subgroup, highlighting the difference between these subgroups." (PMID 37428418, 2023).
breast carcinoma (continued). "Moreover, Foxp3 blockade in vivo reduced the metastatic potential of breast cancer cells." (PMID 37766222, 2023). "FOXP3+ Treg cells have been found to be significantly elevated in peripheral blood as well as tumor tissues, and upregulated infiltration predicted poor prognosis in a variety of cancers, including breast cancer, melanoma, non-small cell lung cancer, and gastric cancer." (PMID 37047824, 2023). "In conclusion, our findings highlighted the association of Foxp3+ lymphocytes with negative clinicopathological features and shorter overall survival (OS), thus confirming the role of Tregs as a negative prognostic marker in canine mammary carcinomas." (PMID 36766393, 2023). "Therefore, the immunosuppressive function directed through FOXP3 + T cells may play an essential role in the biology of ER + breast cancer." (PMID 37115435, 2023). "Furthermore, other types of cancer like HNSCC or breast cancer should also be investigated more closely for functionally heterogenous FoxP3+ T cell subpopulations, as this feature and its prognostic relevance might not be limited to RC." (PMID 35140715, 2022). "Therefore, we posit that SI-2 treatment might have a dual function in suppressing breast cancer progression by reducing the Treg population and blocking Foxp3 function in breast cancer cells." (PMID 36316775, 2022). "Furthermore, apart from breast cancer, one of the studies pointed out that the upregulation of FOXP3 in gastric cancer cells put a brake on GC cell growth in both in vivo and in vitro studies, unraveling the crucial role of FOXP3 expression in different carcinomas." (PMID 34938323, 2021). "After transfer, these Tregs lose their FoxP3 expression and migrate into B-cell follicles, in which they differentiate into TFH cells on CD40/CD40L-dependent interaction with B cells and consistent with the detection of TFH in breast cancer- and NSCLC-associated TLS." (PMID 33763071, 2021). "However, the relationship between immune cell subpopulations, such as CD4+, CD8+, and FOXP3+, in breast cancer, especially in triple negative carcinoma (TNC), remains unclear." (PMID 32222891, 2020). "However, opinions vary among researchers regarding the role of FOXP3 + in breast cancer." (PMID 32222891, 2020). "However, the relationship between immune cells subpopulations, such as CD4+, CD8+ and FOXP3+, in breast cancer, especially in TNC, remains unclear." (PMID 32222891, 2020). "Therefore, the prognostic value of FOXP3+ TILs may be affected by breast cancer molecular subtypes and interactions with other immune cells." (PMID 31852159, 2019). "Finally, the Foxp3+ regulatory T cells (Treg) that create an immunosuppressive tumor microenvironment, allowing escape from immunosurveillance, and consequently, enhancing breast carcinoma progression." (PMID 31145753, 2019). "Surgically resected samples from 156 patients with invasive breast cancer (BC) were assessed for the expression of FOXP3 and CCL20 by immunohistochemistry." (PMID 31852159, 2019). "On the basis of this analysis, we wondered whether FOXP3 could regulate breast cancer angiogenesis." (PMID 29970908, 2018). "Because Treg infiltration in both melanoma and breast cancer has been associated with poor prognosis, we investigated whether any of the applied cancer models in BRGS‐HIS mice recruited Tregs (FoxP3+) cells." (PMID 30120895, 2018). "Therefore, we investigated whether FOXP3 is involved in the regulation of breast cancer angiogenesis." (PMID 29970908, 2018). "These indicated that FOXP3 could interact with Gal-1 in breast cancer cells." (PMID 29549328, 2018). "Additionally, through in vivo tumor xenograft assays and in vitro functional experiments, we confirmed that FOXP3 overexpression could inhibit breast cancer angiogenic activity." (PMID 29970908, 2018).
breast carcinoma (continued). "Finally, an inverse correlation between nuclear FOXP3 expression and VEGF expression was also observed in human breast cancer samples, and FOXP3 downregulation and VEGF upregulation were both correlated with reduced survival in breast cancer data sets in the Kaplan–Meier plotter." (PMID 29970908, 2018). "However, in this study, all tumor samples showed cytoplasmic or both cytoplasmic and nuclear FOXP3 expression, suggesting frequent deregulation of FOXP3 localization and failure to translocate to the nucleus in breast cancer cells and explaining the correlation with worse prognosis." (PMID 28713192, 2017). "Although we have not found these to be associated with PD-L1 or FOXP3 expression in PBMCs in breast cancer metastases, these factors could nonetheless contribute to immune evasion." (PMID 26942414, 2017). "Interestingly, investigation of heterozygous Scurfy mice Foxp3sf/+ revealed that they also harbored hepatoma, in addition to mammary tumors, suggesting that FOXP3 may have an impeditive role in hepatocarcinogenesis." (PMID 28903735, 2017). "Finally, facilitate Runx1/Foxp3 interaction could be use to improve anti-tumor strategies in breast cancer therapy." (PMID 26735887, 2016). "These may account for the poor overall survival in breast cancers with higher FOXP3+ TILs level." (PMID 27566250, 2016). "The aims of our study were to use meta-analysis to demonstrate the correlation between FOXP3+ TILs and the clinicopathological characteristics of breast cancer and evaluate whether detection of FOXP3+ TILs can act as a clinical predictor for patients with breast cancer." (PMID 26475790, 2015). "In addition, we also confirmed that numbers of tumor-infiltrating FoxP3+ cells in breast cancer were also positively correlated with tumor stages and lymph nodal status, but strongly negatively correlated with relapse-free survival (RFS) and overall survival (OS)." (PMID 25968569, 2015). "However, it is also true that the prognostic roles of FOXP3 remain controversial; for instance, breast cancers with FOXP3+ TIL have been reported to be less sensitive to cytotoxic chemotherapy and have a worse prognosis, but others reported that those with FOXP3+ TIL have a better prognosis." (PMID 26341640, 2015). "Results from this study demonstrate that, in breast cancer, the presence of high levels of FOXP3+ TILs is associated with young age, high grade, positive nodal status, concurrent CD8+ T-cell infiltrates, and ER negativity (including both the HER2+/ER– and core-basal subtypes)." (PMID 25193543, 2014). "Most of the studies reporting that FOXP3+ TILs are an indicator of poor prognosis in breast cancer applied unstratified survival analyses and might be expected to largely reflect the majority ER + population, possibly confounded by an opposite association in ER– cases." (PMID 25193543, 2014). "Additionally, intratumoral Tregs were demonstrated to predict worse OS in cyclooxygenase-2-positive uveal melanoma while the relationship between Foxp3+ cells and clinical outcome has been tested repeatedly in breast cancer subtypes according to estrogen receptor." (PMID 24276989, 2014). "FOXP3+ iTILs were an indicator of poor survival in ER − tumors, but a favorable prognostic indicator in ER − breast cancers, indicating that the interaction of FOXP3+ iTILs with ER status could mitigate the prognostic effect of FOXP3+ TILs in the unstratified breast cancer population." (PMID 25193543, 2014). "Similarly, poor RFS was also seen among patients with higher FOXP3 expression in HER2−/ER+ breast cancer (P<0.0001, n = 832, Kaplan-Meier Estimates survival analysis), and the median RFS in tumors with high expression and others were 7.83 and 15.93 years, respectively." (PMID 23341929, 2013). "However, clinical implications of FOXP3 expression in breast cancer cells are contradictory." (PMID 23861693, 2013). "Therefore, the prognostic value of FOXP3 expression in breast cancer remains controversial." (PMID 24649219, 2013).
breast carcinoma (continued). "Furthermore evidence has been reported that localization and activation status of FOXP3 positive cells might play a prognostic role in breast cancer." (PMID 22471961, 2012). "Moreover, FOXP3 also plays a role in breast cancer, as FOXP3fl acts as repressor of Her-2." (PMID 19568423, 2009). "Specifically, the authors assessed the status of PD-L1, PD-1, CTLA-4, CD68, CD163, CD11c, iNOS, CD3, CD8, CD4, FOXP3, CD20, and Ki67 along with pan Cytokeratin and CD31 in the TME of 3098 tumors, including 587 cases with breast cancer." (PMID 40243442, 2025). "In breast cancer, they demonstrated that inflamed tumors (i.e., having high CD8, CD4, FOXP3, and dendritic cell density) along with increased PD-L1 expression on tumor cells and immune cells were associated with prolonged OS." (PMID 40243442, 2025). "Lacidipine potently augmented the anti‐tumor effects of chemotherapeutic agents on breast cancer in vivo by activating CD45+CD8+ effector T cells and incapacitating CD4+CD25+Foxp3+ Tregs." (PMID 39585774, 2025). "In triple-negative (TN) subtype breast cancer cells, the ratio of infiltrating CD8+ T cells to FOXP3+ T cells was significantly negatively correlated with GPR81 expression." (PMID 40650086, 2025). "In murine breast cancer models, depletion of Tregs using anti-CD25 antibodies or genetic ablation (FoxP3-Diphtheria Toxin system) enhances CD8+ T cell infiltration and delays tumor progression, confirming their direct role in suppressing anti-tumor immunity." (PMID 41550427, 2025). "Conversely, numerous studies have shown that Foxp3+ Tregs also express CD20+ and can be indicative of poor prognosis in breast cancer." (PMID 38533507, 2024). "In breast cancer patients, TGF-β produced by CAFs or M2 macrophages promoted the differentiation of CD4+ T cells into Tregs (FOXP3+ CD4+)." (PMID 39596815, 2024). "In breast cancer, FAP+ CAFs particularly the ECM-myCAF and TGFβ-myCAF clusters, increase PD-1 and CTLA-4 expression on the surface of CD4+CD25+FOXP3+ Tregs." (PMID 37166418, 2023). "Our study has shown that ILC patients with low density of CD4, CD8, CD20, CD56, CD68, and FOXP3 had significantly longer DFS and OS, in contrary to TILs in TNBC and HER2‐positive breast cancer." (PMID 38151972, 2023). "Different subtypes of breast cancer can be identified using DSP technology; for example, regulatory T cell markers (CD4, CD25, and FOXP3) are highly expressed in basal-like and luminal breast cancers." (PMID 37744276, 2023). "In breast cancer, gastric cancer, prostate cancer, and HCC, tumor FOXP3 acts as a tumor suppressor that inhibits the expression of multiple oncogenes." (PMID 37868998, 2023). "Breast cancer, prostate cancer, and gastric cancer had better prognoses than NSCLC, colorectal cancer, and cervical cancer when FOXP3 is overexpressed." (PMID 37626655, 2023). "Our data, while preliminary, would support combined regimens of immunotherapy or chemotherapy with the addition of FoxP3+ and CD163+ macrophage-targeting agents in breast cancer." (PMID 36551693, 2022). "Previous studies have found that in breast cancer, PDGFRB+CAFs recruit CD4+CD25+FOXP3+ Treg cells, and the recruited Treg cells inhibit the activation and proliferation of CD8+T cells in the TME, thereby inducing local immunosuppression." (PMID 35967414, 2022). "FOXP3 + and CD8 + are recognized markers of tumor-infiltrating lymphocytes (TILs) for breast cancer." (PMID 35438346, 2022). "High FoxP3+ TIL counts were reported in metastatic lymph nodes in other malignancies such as non-small cell lung carcinoma, breast cancer and cervical cancer." (PMID 35597869, 2022). "To date, not only the CD8+ and FoxP3+ TIL counts but also the FCR has been reported as prognostic predictors in several malignancies, such as non-small cell lung carcinoma, breast cancer, and gastroenterological malignancies." (PMID 35597869, 2022).